ZBTB47 (zinc finger and BTB domain containing 47)
Description:
May be involved in transcriptional regulation.
Synonyms: KIAA1190; ZNF651; DKFZp434N0615
Tractability: PROTAC: UniProt records ubiquitination sites on it.
Gene: Protein-coding gene on chromosome 3 (42,652,900 to 42,667,580, forward strand). Ensembl gene ENSG00000114853.
Subcellular location: Nucleus
Subcellular location (Human Protein Atlas): Nucleoplasm
Gene Ontology:
Molecular function: protein binding; DNA-binding transcription factor activity, RNA polymerase II-specific
Biological process: regulation of transcription by RNA polymerase II
Cellular component: nucleus
Genetic constraint (gnomAD): Loss-of-function variants: 22 observed, 46.49 expected, observed/expected ratio (o/e) 0.47, 90% interval 0.34 to 0.68. The upper end of that interval is the gene's LOEUF score, 0.68, which puts it in group 2 of 6, group 1 being the genes least tolerant of losing a copy. Missense variants: 771 observed, 915.19 expected, observed/expected ratio (o/e) 0.84, 90% interval 0.79 to 0.89. Synonymous variants: 385 observed, 378.55 expected, observed/expected ratio (o/e) 1.02, 90% interval 0.94 to 1.11.
Homologues: Orthologues: chimpanzee ZBTB47 (99% identical), macaque ZBTB47 (99% identical), pig ZBTB47 (94% identical), dog ZBTB47 (92% identical), rabbit ZBTB47 (91% identical), mouse Zbtb47 (80% identical), rat Zbtb47 (80% identical), guinea pig ZBTB47 (75% identical), tropical clawed frog zbtb47 (61% identical), zebrafish zbtb47a (51% identical), zebrafish zbtb47b (40% identical), Drosophila melanogaster CG6654 (13% identical), and 2 more. Paralogues in human: ZNF652 (44% identical), ZNF324 (19% identical), ZNF324B (18% identical), ZNF513 (15% identical), GTF3A (12% identical), ZUP1 (9% identical).
Diseases named in the same sentence as ZBTB47 in open-access papers:
ZBTB47 is named in the same sentence as 4 diseases in open-access papers, as found by Europe PMC text mining. Sharing a sentence is not in itself a finding about the gene and the disease.
ZBTB47 shares sentences with these, for which no sentence is quoted: breast carcinoma (1 paper); digestive system carcinoma (1); glioma (1); tumour (1).